EDNRB (endothelin receptor type B)
Diseases named in the same sentence as EDNRB in open-access papers (continued):
Sharing a sentence is not in itself a finding about the gene and the disease.
Hirschsprung disease (41 papers, 2010 to 2026). Hirschsprung disease (HSCR) is a congenital intestinal motility disorder that is characterized by signs of intestinal obstruction due to the presence of an aganglionic segment of variable extent in the terminal part of the colon. "The spotting lethal (sl/sl) rat has a naturally occurring null mutation in the EdnrB gene, a mutation which also occurs in some human patients resulting in Hirschsprung disease." (PMID 35111975, 2022). "In a proof of principle example, RUNNER successfully recaptured (P< 2.5E-6) the known causal gene RET, and prioritized another known gene EDNRB of Hirschsprung disease." (PMID 34931221, 2022). "Heterozygous EDNRB c.553G>A mutation has been reported previously as a dominant pathogenic mutation in Chinese patients with Hirschsprung disease (PMID: 16944573)." (PMID 33095980, 2020). "Previous evidence indicates that inactivation of the endothelin receptor B (EDNRB) gene in the mouse causes aganglionic megacolon with spotted coat coloring, and EDNRB mutations are known to be associated with Hirschsprung disease in patients with Shah-Waardenburg syndrome." (PMID 24736498, 2014). "Variants in EDNRB may cause Waardenburg syndrome and Hirschsprung disease." (PMID 39651291, 2024). "The idea answer is: Coding sequence mutations in RET, GDNF, EDNRB, EDN3, and SOX10 are involved in the development of Hirschsprung disease." (PMID 40766492, 2025). "The deletion in rat spans the distal half of the first coding exon and the proximal part of the adjacent intron of EdnrB and results in a Hirschsprung disease phenotype in these rats." (PMID 35111975, 2022). "EDNRB has been identified as a disease‐causing gene for Waardenburg syndrome type IV (WS4) and Hirschsprung disease." (PMID 33095980, 2020). "We observed facility-specific microbiome signatures in the context of a disease model [the Ednrb (endothelin receptor type B) Hirschsprung disease mouse] and in normal C57BL/6J mice." (PMID 30079054, 2018). "This so called “lethal white foal syndrome” thus closely resembles Hirschsprung disease in humans with EDNRB defects." (PMID 27329507, 2016). "Consequently, EDNRB variants demonstrate a more intricate interaction than that exhibited by simple dominant or recessive traits, thereby suggesting that homozygous variants may result in isolated Hirschsprung’s disease, while heterozygous variants may be associated with WS4." (PMID 40650035, 2025). "Moreover, in the WS4 cases associated with EDNRB and EDN3 pathogenic variants, the characteristic presentation of Hirschsprung disease caused by enteric nervous system disorder was inconclusive." (PMID 41516007, 2025). "Mutations in EDNRB have been identified in patients suffering from Hirschsprung’s disease, which is characterized by the absence of neural crest-derived intramural ganglia along the colon." (PMID 27188386, 2017). "Mutations in the genes encoding the EDN receptor B (EDNRB), its ligand EDN3, and the transcription factor SOX10 cause Waardenburg-Shah syndrome (also known as Waardenburg syndrome type IV), comprised of pigment cell abnormalities and Hirschsprung’s disease." (PMID 24040226, 2013). "Several studies reported that mutations of EDNRB were identified in Hirschsprung disease (HSCR, absence of enteric neurons in distal portions of the gut) and Waardenburg syndrome type 4A (WS4A, pigmentation defects and deafness due to altered development of melanocytes)." (PMID 35045821, 2022). "In spite of having another variant in EDNRB, Hirschsprung disease was absent." (PMID 34276053, 2021). "Nevertheless, EDNRB has been involved in peripheral microvascular function, cancer development and in the development of different hereditary diseases like Waardenburg syndrome or Hirschsprung disease and, therefore, EDNRB is also involved in the alteration of enteric neurons." (PMID 25799405, 2015).
Hirschsprung disease (continued). "If true, this explanation for the expression of EDN3 in our cultures and its down-regulation by RA supports an interaction of RA and EDNRB signaling in the expression of Hirschsprung’s disease, albeit in a non-neural crest autonomous fashion." (PMID 24040226, 2013). "Although a homozygous mutation of c.553G>A(p.V185M) in EDNRB was identified by WES in this family, no other characteristic symptoms, such as Hirschsprung disease and depigmented patches of the skin and hair, were found in our patients, suggesting atypical WS4 disease." (PMID 33095980, 2020). "However, this gene has never been involved in GI complaints, despite being recently described as one of the regulators of the Endothelin Receptor Type B (EDNRB) expression, a known Hirschsprung disease (HSCR) gene involved in GI development and function." (PMID 35874825, 2022).
Hypertension (26 papers, 2008 to 2025). The presence of chronic increased pressure in the systemic arterial system. "In mammals, two independent endothelin receptors, EDNRA and EDNRB, have been linked to high-altitude pulmonary edemas (Sharma, Singh & Sarkar, 2014), as well as hypertension, cardiac hypertrophy, and coronary artery disease (Schneider, Boesen & Pollock, 2007)." (PMID 29018624, 2017). "Candidates EDNRA, EDN1 and EDNRB function together in a regulatory pathway with endothelin-converting enzyme ECE1, which has been implicated in essential hypertension." (PMID 20886000, 2010). "This completely novel in vivo model of hypertension and possibly IA induction can be the basis for further studies, which may include investigations of EDNRB as well as the observation of the outcome of SAH followed by IA rupture." (PMID 36138975, 2022). "Although the mechanism of EDNRB regulation by lead is unknown, an increase of its expression may contribute to the hypertension observed in low-level lead exposures." (PMID 22839698, 2012). "Importantly, endothelins are associated with the onset of preeclampsia in humans, and hypertension linked with placental ischemia in EDNRB-negative mice can be partially reversed by targeting downstream factors from receptor B50." (PMID 36535952, 2022).
pulmonary arterial hypertension (20 papers, 2014 to 2026). Pulmonary arterial hypertension (PAH) is a group of diseases characterized by mean pulmonary artery pressure >20 mmHg and elevated pulmonary arterial resistance leading to right heart failure. "Herein, we used bosentan as the endothelin antagonist, which targets two endothelin receptors, EdnrA and EdnrB, with a similar binding affinity and is clinically used to treat pulmonary arterial hypertension." (PMID 38252153, 2024).
ovarian carcinoma (17 papers, 2013 to 2025). A malignant neoplasm originating from the surface ovarian epithelium. "This study is aimed at evaluating serum autoantibodies against four tumor-associated antigens, including LRDD, STC1, FOXA1, and EDNRB, as biomarkers in the immunodiagnosis of ovarian cancer (OC)." (PMID 35273656, 2022). "In renal cell carcinoma, both EDNRB-442 and EDNRB-532 are associated with tumors with increased pAKT at S473, while in ovarian cancer, there was only a slight association between EDNRB-442 and pAKT_S473." (PMID 32201539, 2020). "We analyzed EDNRB exon expression data and RPPA data from The Cancer Genome Atlas for both renal cell carcinoma and ovarian cancer." (PMID 32201539, 2020). "Interestingly, while EDNRB expression did not significantly predict patient outcome in liver and ovarian cancer, high EDNRB 436/442 and EDNRB-532 expression predicted improved patient outcome in renal cell carcinoma, suggesting cancer type-specific effects of EDNRB on patient outcome." (PMID 32201539, 2020).
Waardenburg syndrome (16 papers, 2011 to 2025). A disorder characterized by varying degrees of deafness and minor defects in structures arising from neural crest, including pigmentation anomalies of eyes, hair, and skin. "Mutations in the EDNRB gene were identified in the Waardenburg syndrome, with clinical pigmentation defects due to abnormal development of melanocytes." (PMID 33178831, 2020). "Mutations of different genes like MITF (microphthalmia-associated transcription factor), PAX3 (Paired Box Gene 3), SOX10, and EDNRB (endothelin receptor type B, gene) have been noted in causing mild or incomplete phenotypic expression of symptoms in Waardenburg syndrome." (PMID 31998473, 2020). "Genetic studies suggest that Waardenburg syndrome is caused by mutations of PAX3 and other genes such as MITF, SOX10, EDN3, EDNRB and SNAI21,9,13,35–37." (PMID 38278860, 2024). "For example, EDNRB and SOX10 mutations together cause human Waardenburg syndrome." (PMID 40002960, 2025). "Similarly, Waardenburg syndrome (EDNRB) and Van der Woude syndrome 1 (IRF6) have also been reported in autosomal dominant modes." (PMID 41229399, 2025). "Six genes involved in Waardenburg syndrome include PAX3 (encoding the paired box 3 transcription factor), MITF (microphthalmia-associated transcription factor), EDN3 (endothelin 3), EDNRB (endothelin receptor type B), SOX10 (encoding the Sry bOX10 transcription factor), and SNAI2 (snail homolog 2)." (PMID 35790984, 2022). "However, in the phenotypically similar Waardenburg syndrome in humans, these phenotypes are associated with EDN3, SOX10, and EDNRB." (PMID 32616020, 2020). "Thus, possible candidates for white coat colour (KIT on BTA6, KITLG on BTA5, PMEL on BTA5, TYR on BTA29) and other Waardenburg syndromes (WS) including PAX3 (WS1, WS3; on BTA2), EDNRB (WS4a; on BTA12), EDN3 (WS4b; on BTA13) and SOX10 (WS2e, WS4c; on BTA5) could be clearly excluded." (PMID 22174915, 2011). "Although the Waardenburg syndrome genes PAX3, SOX10, MITF, EDN3 and EDNRB were not dramatically affected at the mRNA level, expression of the piebaldism gene KIT was significantly down-regulated upon loss of YY1." (PMID 22570637, 2012).
breast carcinoma (14 papers, 2004 to 2025). "The EDNRB biomarkers are additionally linked to breast cancer, colorectal cancer, and prostate cancer." (PMID 40014586, 2025). "First, we used a primer pair detecting all 7 of the major GPCR-encoding isoforms (EDNRB-all) to amplify cDNA from breast cancer cells." (PMID 32201539, 2020). "In contrast to our findings in breast cancer, analysis of renal cell carcinoma revealed that EDNRB-532 expression was associated with significantly improved survival outcomes." (PMID 32201539, 2020). "For instance, NDST1, FRZB, ALAD, EDNRB, SSX2IP, and SFN have strong associations with breast cancer development, which bolsters our confidence in the viability of our model." (PMID 38007443, 2023). "In the present study, we focused on characterizing the expression of function of EDNRB isoforms in breast cancer cells to more clearly understand the role of EDNRB in breast cancer." (PMID 32201539, 2020). "In this study, we assessed the mRNA expression of the major endothelin B receptor gene (EDNRB) isoforms and found differences in both mRNA and protein expression in normal breast cells and breast cancer cell lines." (PMID 32201539, 2020). "The results of our ET-3 stimulated invasion assays reveal an inhibitory role of ET3-stimulated EDNRB on breast cancer invasion, in contrast to the pro-invasive role of ET1-stimulated EDNRB reported by Hagemann et." (PMID 32201539, 2020). "In this study, we report for the first time that EDNRB isoforms are differentially expressed across multiple breast cancer cell lines." (PMID 32201539, 2020). "Normal breast tissue and uninvolved breast tissue from breast cancer patients showed higher expression than cancer samples when amplified with primers recognizing all EDNRB isoforms and with EDNRB-532 specific primers." (PMID 32201539, 2020). "Together, these results demonstrate difference in EDNRB isoform expression in breast cancer cell lines." (PMID 32201539, 2020). "We next assessed EDNRB protein expression in normal and breast cancer cell lines by Western blotting." (PMID 32201539, 2020). "We designed the present study to help clarify how EDNRB regulates breast cancer progression by introducing two novel components." (PMID 32201539, 2020). "Because EDNRB has been proposed to serve as a negative regulator of endothelin A receptor signaling (EDNRA) 5,9, and considering that EDNRA is a well-known promoter of breast cancer progression 19, EDNRB is expected to be an antagonist to breast cancer." (PMID 32201539, 2020). "Together with the results of the previous figure, this suggests that in the presence of ET3, EDNRB-442 negatively regulates invasion and EDNRB-532 promotes cell viability in breast cancer cells." (PMID 32201539, 2020). "We designed primers spanning various isoform-specific exons in the EDNRB gene to determine the relative abundance of the major EDNRB isoforms in breast cancer cell lines and normal mammary epithelial cells (HMECs)." (PMID 32201539, 2020). "Specifically, we found that EDNRB isoform expression differed amongst breast cancer cell lines and between normal and cancer cells." (PMID 32201539, 2020). "The drug bosentan, which targets both EDNRA and EDNRB, inhibits tumour growth, vascularisation and bone metastasis in breast cancer." (PMID 19527488, 2009). "While there are numerous reports characterizing EDNRB expression in breast cancer, our research adds to the knowledge of endothelin B receptor (EDNRB) in breast cancer by showing differences in both the expression and function of specific EDNRB isoforms in breast cancer cells." (PMID 32201539, 2020). "When comparing EDNRB mRNA and protein expression in breast cancer cells, we found that the MCF-7 cancer cell line had the highest EDNRB expression of the cell lines tested, while normal breast epithelial cells (HMECs) did not express detectable levels of EDNRB." (PMID 32201539, 2020).
breast carcinoma (continued). "Thus, we believe our data support a general effect of EDNRB-442 on breast cancer cell invasion and AKT1 activation across subtypes." (PMID 32201539, 2020). "Differences in breast cancer cell line expression and breast tumor expression may indicate the involvement of stromal cells in EDNRB isoform expression." (PMID 32201539, 2020). "Together, these results establish novel isoform-specific roles for EDNRB in breast cancer cells." (PMID 32201539, 2020). "Together, our results provide some explanation of the previous contradictory results regarding the endothelin B receptor in breast cancer and support a more complex model of the involvement of EDNRB in its regulation of breast cancer progression that is isoform, ligand, and subtype specific." (PMID 32201539, 2020). "However, most of the studies published on EDNRB in breast cancer characterize it as a cancer promoter 12,14-16,20." (PMID 32201539, 2020). "Second, by studying specific isoforms of EDNRB we also describe distinct roles for the EDNRB-442 and EDNRB-532 isoforms that may explain some of the conflicting reports regarding the contribution of EDNRB to breast cancer progression." (PMID 32201539, 2020). "Importantly, we also report that EDNRB-442 is the primary isoform responsible for ET3-induced inhibition of cancer cell invasion and activation of pAKT1, while EDNRB-532 promotes cell viability in some breast cancer cell lines." (PMID 32201539, 2020). "The literature is somewhat conflicted regarding whether EDNRB expression and activity in breast cancer cells promotes breast cancer or inhibits its progression." (PMID 32201539, 2020). "We next asked whether EDNRB mRNA expression correlates with breast cancer patient survival." (PMID 32201539, 2020). "Because AKT1 is a known negative regulator of invasion in breast cancer cells, our findings suggest that EDNRB-442 activates AKT1 and thereby inhibits breast cancer invasion." (PMID 32201539, 2020). "Because the downstream effects of EDNRB are likely affected by the presence of its major ligands, ET1 and ET3 (encoded for by EDN1 and EDN3, respectively), we also analyzed survival in breast cancer subtypes by relative combined expression of EDNRB/EDN3 and EDNRB/EDN1 mRNA." (PMID 32201539, 2020). "Analysis of breast cancer samples from TCGA revealed a non-significant trend of increased pAKT at both S743 and T308 in EDNRB-high breast cancer samples from basal, but not luminal subtypes or uninvolved breast tissue." (PMID 32201539, 2020). "Consistently, our data show a EDNRB-442 induced increase in ET3-stimulated pAKT1 signaling in breast cancer cell lines, while none of the EDNRB isoforms altered ERK activation, suggesting that ET3/EDNRB signaling primarily functions through the PI3K pathway." (PMID 32201539, 2020). "Furthermore, chemically inhibiting EDNRA inhibits invasion in breast cancer cell lines 19, and ET1 and ET2 both induce breast cancer cell migration in an EDNRA and EDNRB-dependent manner 16,20." (PMID 32201539, 2020). "Isoform expression differences between normal cells and cancer cells, and potential functional differences of these EDNRB isoforms in cancer have not been previously reported in breast cancer." (PMID 32201539, 2020). "The precise role of the ET3-activated endothelin B receptor (EDNRB) signaling in cancer remains unclear, and the effects of ET3-stimulated EDNRB in breast cancer are not fully understood." (PMID 32201539, 2020). "Previous studies have examined EDNRB mRNA and protein expression in breast cancer cell lines, but to our knowledge, expression analysis of specific EDNRB isoforms has not been previously reported in breast cancer." (PMID 32201539, 2020). "Knocking down the EDNRB gene in breast cancer cells altered invasiveness toward endothelin 3 (ET3), and we observed EDNRB isoform-specific regulation of breast cancer cell invasion and cell signaling, as well as isoform- and subtype-specific differences in breast cancer patient survival." (PMID 32201539, 2020).
breast carcinoma (continued). "Notably, an ET-axis expression pattern similar to that of breast cancer was recently found in cervical cancer; that is, upregulation of EDN1, EDN2, EDNRA and EDNRB expression was accompanied by downregulation of EDN3 expression in cancerous cervix as compared with normal cervical epithelium." (PMID 19527488, 2009). "Together with the previous results, we conclude that EDNRB, particularly EDNRB-442, regulates AKT1 activation in some, but not all, breast cancer cells, and that this effect may also be present in other cancer types such as kidney cancer." (PMID 32201539, 2020). "Although a previous study found that over-expressing and knocking down EDNRB in two breast cancer cell lines altered invasion toward endothelin-1 (ET1) 16, EDNRB-regulated invasion toward ET3 and isoform-specific effects on breast cancer invasion have not been widely studied." (PMID 32201539, 2020).